PRL (prolactin)
Diseases named in the same sentence as PRL in open-access papers (continued):
Sharing a sentence is not in itself a finding about the gene and the disease.
hyperprolactinemia (continued). "Thus, activation of hypothalamic dopaminergic neurotransmission by dopamine agonists can reduce incidence and prevalence of MetS in patients with hyperprolactinaemia by controlling of PRL release and improving of insulin sensitivity." (PMID 39663784, 2024). "The existence of extrapituitary prolactin and its role as a cytokine at the local level as well as the fact that the endometrium is one of the sources of extrapituitary prolactin suggest a possible relationship between prolactin/hyperprolactinaemia and endometriosis-related infertility." (PMID 39407928, 2024). "Clinical studies on the influence of prolactin and hyperprolactinaemia in endometriosis." (PMID 39407928, 2024). "The commonly used methods to improve antipsychotic-induced hyperprolactinemia include reducing the doses of the antipsychotic, switching to another antipsychotic that has a lesser effect on prolactin, adding a dopamine agonist, adding aripiprazole, and adding metformin." (PMID 38505795, 2024). "In addition, the median recurrence time after surgery was shorter in patients with hyperprolactinemia than in those with normal PRL levels." (PMID 37762304, 2023). "Hyperprolactinemia, in which circulating PRL levels are higher than those in the reference population, may result in decreased sperm production, and infertility in men; and lead to decreased LH and FSH levels in rats." (PMID 37954671, 2023). "Of note, no significant dose correlation was found for changes in the serum prolactin concentration, and no associated hyperprolactinemia was reported after patients received 1-week HSK21542, contrary to the actions of nalfurafine hydrochloride." (PMID 37876731, 2023). "Prolactin (PRL) is a recommended biomarker in the initial diagnostic workup to rule out hyperprolactinemia (HPRL)." (PMID 38004264, 2023). "Antipsychotics usually increase serum prolactin levels in both adults and younger patients, but no study has reviewed the potential association between sex and vulnerability for developing hyperprolactinemia among children and adolescents." (PMID 36305138, 2023). "Moreover, hyperprolactinemia was present in 20% of the patients, but the conception rate and pregnancy outcome were similar in patients with normal prolactin levels and those having hyperprolactinemia." (PMID 36678618, 2023). "One of them is hyperprolactinemia, which is usually defined as an increased level of PRL." (PMID 36833950, 2023). "Likewise, in Phase 2 study, 48 participants presented normal PRL levels (mean = 9.81 ± 4.11), and the remaining 12 displayed hyperprolactinemia (mean = 66.04 ± 23.17), of which one patient (8.3%) presented normalized PRL during testing." (PMID 36596817, 2023). "However, its administration at times elevates serum prolactin levels, which can lead to pathological hyperprolactinemia." (PMID 38249246, 2023). "Prolactin levels are usually higher in the patients with PCOS, and hyperprolactinemia may be associated with anovulation." (PMID 36823522, 2023). "Despite the myocardial prolactin (PRL) binding activity and the known effect of enhancing contractility in the isolated rat heart, little information is available concerning the cardiovascular consequences of hyperprolactinemia in humans." (PMID 36836192, 2023). "During controlled ovarian stimulation (COS) for assisted reproductive technology a particular dynamic of serum prolactin level, characterized by transient hyperprolactinemia, was also reported with incompletely known significance and impact on fertility treatment outcome." (PMID 36678618, 2023). "This increase may be explained by the observed hyperprolactinemia since prolactin and STAT5 are known transcriptional activators of CITED2, HSPA5 and PIM1." (PMID 36694114, 2023). "In the same line, it has been described that GH tumors causing hyperprolactinemia were larger than those without PRL increase." (PMID 37762304, 2023).
hyperprolactinemia (continued). "Also, there was a significant difference in SLEDAI score between SLE patients with normal prolactin levels and hyperprolactinemia (P value = 0.004)." (PMID 37864188, 2023). "In fact, the acute elevation of PRL may affect the immune response, instead the persistence of hyperprolactinemia may induce adaptive changes." (PMID 36658300, 2023). "Hypogonadism in hyperprolactinemia may be reversible due to the inhibitory effect of prolactin on the gonadotrophic hormones from the prolactin, or irreversible, secondary to the destruction of gonadotrophic cells." (PMID 36835974, 2023). "These variations of serum PRL levels, which may be influenced by estrogens concentrations, might also explain the differences in sensitivity to AP induced hyperprolactinemia between sexes found across the lifespan." (PMID 36305138, 2023). "Patients with SLE may develop hyperprolactinemia due to either increased pituitary prolactin secretion under the influence of inflammatory cytokines or increased synthesis of prolactin by peripheral lymphocytes." (PMID 37864188, 2023). "Persistent hypogonadism despite a normalization of PRL obtained with DA may be the result of suppression of gonadotropins by longstanding hyperprolactinemia in combination with the mass effect of the tumor on normal pituitary tissue." (PMID 37403202, 2023). "On the other hand, treatment for hyperprolactinemia might interfere with the possible beneficial effects of prolactin on other aspects of reproductive function." (PMID 36678618, 2023). "Also, the present study revealed higher SLEDAI scores among SLE cases with hyperprolactinemia than those with normal prolactin levels (P value = 0.004)." (PMID 37864188, 2023). "In order to determine whether a woman has PCOS in addition to hyperprolactinemia, prolactin levels have to be normalized before the diagnosis PCOS can be made." (PMID 37854182, 2023). "Overall, 111/178 participants (62.4%) reported ≥1 TEAE; most common (>5%) TEAEs were headache (13.5%) and increased blood prolactin/hyperprolactinemia (18.0%); 8/178 (4.5%) participants experienced serious TEAEs, and 6/178 (3.4%) participants withdrew due to TEAEs." (PMID 37480362, 2023). "Hyperprolactinemia affects dendritic cell function, switching from an antigen-presenting to a pro-inflammatory phenotype In parallel, same cytokines (IL-1, -2, and -6) stimulate the secretion of PRL." (PMID 36658300, 2023). "However, it appears that VAC can be able to impact on PRL secretion in selected patients, especially those with only mild hyperprolactinaemia, and in general terms seems to be a safe and well tolerated phytotherapic agent." (PMID 38075075, 2023). "However, the remaining 31 patients presented with hyperprolactinemia with a mean PRL of 57.85 ± 42.8, which then significantly reduced to 51.75 ± 38.56 (p = 0.005)." (PMID 36596817, 2023). "Although the mechanisms of hyperprolactinemia in CKD are yet to be unraveled, it could be a result of PRL accumulation due to deficient renal clearance." (PMID 35173591, 2022). "The PRL regulatory loop might be disrupted in CKD since elevated concentrations of PRL or hyperprolactinemia are present in ∼30% of the patients in the early stages and 60–80% in the advanced stages of CKD." (PMID 35173591, 2022). "Hyperprolactinemia is the hallmark not only of PRL-secreting tumors but also of non-secreting neoplasms of the hypothalamo-pituitary region and of a variety of disorders that must be excluded before prolactinoma is diagnosed." (PMID 35000899, 2022). "The results of the current study seem to be in line with previous observations suggesting that in patients in which hyperprolactinemia treatment leads to normal prolactin levels, cardiometabolic parameters have similar values as in untreated women with normal prolactin levels." (PMID 36195057, 2022).
hyperprolactinemia (continued). "Our study is novel in that we assess the effects of elevated PRL in two hyperprolactinemia states; non-secreting tumors that cause stalk effect and moderately elevated PRL levels, and prolactinoma patients with extremely elevated PRL levels." (PMID 35921360, 2022). "Moreover, a variety of pathological, physiological, and genetic conditions can affect lactotroph cells to increase their PRL secretion, leading to hyperprolactinemia." (PMID 36552931, 2022). "In addition, high prolactin levels have been investigated in patients with DRD2*A1 allele (dopamine receptor); interestingly, patients on clozapine showed hyperprolactinemia, although it was least likely to increase prolactin levels." (PMID 36362270, 2022). "The diagnosis of hyperprolactinemia is established by measuring basal PRL levels." (PMID 35000899, 2022). "Severe drug-related hyperprolactinemia (commonly defined as PRL values above 100 ng/mL), in the context of 100–250 ng/mL (approximately 2120–5300 mIU/L) and > 250 ng/mL (> ~5300 mIU/L), were found to occur in ~30% and ~5% of the cases (particularly with antipsychotics), respectively." (PMID 36313772, 2022). "Prolactin modulates the secretion of sex hormones, so one could expect that hyperprolactinemia will affect the functioning of representatives of both sexes in a different way." (PMID 36581642, 2022). "In a large population-based study including 2,377 participants (1,034 men and 1,343 postmenopausal women) without hyperprolactinemia, aged 40 years and older, in Shanghai, China, low PRL levels were associated with risk of diabetes." (PMID 36704037, 2022). "The magnitude of PRL levels can be useful in determining the etiology of hyperprolactinemia." (PMID 35000899, 2022). "Hyperprolactinemia can threaten many processes in the human body through hormonal disorders, but also through the induction of oxidative stress, which is often overlooked in assessing the effects of excess prolactin in the organism." (PMID 35923861, 2022). "In mild PRL elevation, drug-induced hyperprolactinemia should be considered." (PMID 35892862, 2022). "Additionally, a lower preoperative PRL level was also a strong predictor of a surgically achieved long-term remission of hyperprolactinemia in our study, with a lower recurrence rate." (PMID 35807204, 2022). "Tricyclic antidepressant drugs inhibit dopamine secretion, thus suppressing the inhibitive effect of dopamine on prolactin secretion and might lead to hyperprolactinemia." (PMID 35120473, 2022). "Additionally, hyperprolactinemia was present in 11 of 50 patients, and mean prolactin levels were 19.26 ± 19.69." (PMID 35612842, 2022). "Positive expression of the PRL in the tumor was observed in 7 of these 10 patients, which may suggest co-secretion of PRL as the reason behind hyperprolactinemia." (PMID 35612842, 2022). "Although the subpopulation of women with TSH > 2.5 regardless of ATA status showed a higher risk of hyperprolactinemia, the value of prolactin concentration was not significantly higher than in the rest of the population." (PMID 35329880, 2022). "Pregnant women may experience hyperprolactinemia from even higher levels of prolactin secreted by the immune system, uterus, placenta and mammary glands compared to those who are not pregnant." (PMID 36619589, 2022). "Hyperprolactinemia is diagnosed by measuring plasma prolactin." (PMID 36733805, 2022). "Because high PRL levels are immunosuppressive, the magnitude of the induced hyperprolactinemia (>60 μg/L) could be an explanatory mechanism." (PMID 35721729, 2022). "Second, although our findings were in accordance with previous reports demonstrating no influence of CYP2D6 variation on PRL levels in antipsychotic-induced hyperprolactinemia, some candidate genes associated with changes in PRL were not included in our study." (PMID 36313772, 2022).
hyperprolactinemia (continued). "It has also been reported that the prolactin level was significantly higher in antibody-positive patients, regardless of the clinical diagnosis, and it is considered that the hyperprolactinemia observed in ROHHAD syndrome so far is also consistent with this concept." (PMID 35805903, 2022). "Hyperprolactinemia (hPRL), defined as an excess of prolactin in blood above laboratory reference limits, is also common in women of reproductive age and may mimic the clinical phenotype of PCOS." (PMID 35250884, 2022). "PRL in physiological concentrations plays a role in adipogenesis, adipocyte differentiation, and protection from metabolic syndrome, while in physiological hyperprolactinemia during pregnancy and lactation it presents lipogenic activity." (PMID 36704037, 2022). "Indeed, 15-33% of lupus patients have elevated levels of serum PRL that correlate with disease activity, and individuals with hyperprolactinemia have an increased prevalence of autoantibodies (especially anti-dsDNA)." (PMID 36389691, 2022). "In women suffering from hyperprolactinemia, the number and percentage of circulating DCs and pDCs are reportedly lower, yet it could be controversial regarding PRL relevance to DCs function." (PMID 36389803, 2022). "A high level of prolactin or hyperprolactinemia observed in rats exposed to atrazine at 0.04 and 0.08 mg/L may possibly explain their reduced testosterone level." (PMID 36226274, 2022). "A recent study has proposed that vitamin B6 could reduce prolactin levels, and therefore, the effectiveness of vitamin B6 for reducing serum prolactin in patients with hyperprolactinemia compared with cabergoline was evaluated." (PMID 34737888, 2021). "These are complexes between prolactin and IgG antibodies causing hyperprolactinemia through reduced clearance and are not considered to have any clinical effect." (PMID 34441908, 2021). "This might be partly due to higher base levels of prolactin and higher vulnerability to hyperprolactinemia in response to antipsychotic drugs in women." (PMID 34421613, 2021). "This may be explained by the fact that CN increases prolactin mRNA expression while hyperprolactinaemia alters testosterone production in rat testicular interstitial cells." (PMID 34647003, 2021). "Prevalence rates and degrees of severity of hyperprolactinemia (HPRL) based on PRL concentration may depend on the presence of macroprolactin in the serum." (PMID 33380894, 2021). "Large non-prolactin secreting PAs can compress the portal vessels or damage the pituitary stalk, disrupting the hypothalamic control over pituitary hormone secretion, leading to hyperprolactinemia and pituitary insufficiency." (PMID 33946142, 2021). "Prolactin levels were available from 20 patients, and eight (20%) patients had hyperprolactinemia." (PMID 33909377, 2021). "Furthermore, higher prolactin levels, resulting in hyperprolactinemia has been demonstrated to increase oxidative damage." (PMID 34535150, 2021). "As symptoms of galactorrhea usually persist longer than hyperprolactinemia, in some cases, prolactin levels may have been measured after having already decreased, therefore, explaining the detection of normal values in our sample." (PMID 33768297, 2021). "Consequently, MPRL screening seems to be necessary for some patients with antipsychotics-induced hyperprolactinemia with PRL concentration > 3000 mlU/L." (PMID 33380894, 2021). "Because women have a higher baseline prolactin level than men, the added hyperprolactinemia induced by antipsychotics affects women more than men—it frequently leads to amenorrhea and infertility, hirsutism, acne, osteoporosis, and has been suspected of increasing the incidence of breast cancer." (PMID 34575706, 2021). "Any condition, hypothalamic disorder or medication interfering with dopamine secretion or action (e.g., antipsychotics, some antidepressants) might lead to an increase in prolactin levels, i.e., hyperprolactinemia." (PMID 34441908, 2021).
hyperprolactinemia (continued). "Apparently high levels of prolactin may be due to excess circulating prolactin complexes (‘macroprolactin’) which need to be differentiated from true hyperprolactinemia." (PMID 33963239, 2021). "PRL has indeed been proven to direct growth/differentiation of epithelial cells in the mammary gland throughout gestation, with an experimentally induced late gestational hyperprolactinemia being responsible for higher milk yields." (PMID 33808012, 2021). "FPAs are hormone-secreting PAs, which result in hyperpituitarism, including acromegaly derived from growth hormone (GH)-secreting PAs, hyperprolactinemia derived from prolactin (PRL)-secreting PAs, and Cushing’s syndrome derived from adrenocorticotropin (ACTH)-secreting PAs." (PMID 33841137, 2021). "Similarly, male patients with hyperprolactinemia who took cabergoline showed a rapid decline in prolactin, earlier resolution of gonadal dysfunction, and improved libido compared to those who took bromocriptine." (PMID 33946142, 2021). "An interesting aspect is whether hyperprolactinemia due to treatment with antipsychotic medications might induce a prolactin producing pituitary adenoma." (PMID 34441908, 2021). "Endocrine evaluation showed mild hyperprolactinemia (prolactin (PRL) 482 μIU/ml, normal range 86–324 μIU/ml) and panhypopituitarism, with an insufficient dose of thyroid hormone and an excess of urinary free cortisol (UFC) indicating corticosteroid overtreatment." (PMID 34758866, 2021). "43.5% of patients with hyperprolactinemia had prolactin-positive tumors, suggesting that prolactin hypersecretion by tumor might be a primary etiology in these patients." (PMID 35154007, 2021). "Elevated prolactin levels may also be seen secondary to renal disease, pregnancy, primary hypothyroidism, and drug-induced hyperprolactinemia." (PMID 33946142, 2021). "Hyperprolactinemia (PRL levels > 25 ng/mL) was observed in 84% of the DA exposed." (PMID 33314003, 2021). "True hyperprolactinemia is defined by the presence of excess monomeric prolactin in serum." (PMID 34620143, 2021). "Whether metabolic improvement seen after treatment in patients with hyperprolactinemia reflects the beneficial effects of PRL lowering or of CAB administration is still debated." (PMID 34917030, 2021). "Hyperprolactinemia appears in 18.5%[8.5%; 37.6%], without any real deficiency (no low prolactin was assessed)." (PMID 34922472, 2021). "Indeed, cabergoline, a potent suppressor of pituitary PRL release, has been chronically prescribed to thousands of patients with hyperprolactinemia with minimal ill effects." (PMID 34071395, 2021). "A single PRL level is usually adequate to diagnose hyperprolactinemia." (PMID 34557164, 2021). "Interestingly, hyperprolactinemia and raised plasma prolactin concentrations have been observed to be the possible neuroendocrine mechanism that causes physiological reproductive suppression in non-breeding NMR colony members." (PMID 34535150, 2021). "Whether DRD2 rs1800497 controls bone density through elevated prolactin level or other mechanisms unrelated to hyperprolactinemia requires further investigation." (PMID 32764574, 2020). "In our study, with the platform of Siemens Centaur XP used for PRL measurement, the patients of Group 1 (<40% recovery) and Group 2 (40%‐60% recovery) seemed to be two distinct populations with variable manifestations of classic hyperprolactinemia symptoms." (PMID 32597541, 2020). "According to Majumdar and Sharma, in cases of idiopathic hyperprolactinemia, lowering of PRL levels with continuous treatment with bromocriptine begins earlier, regulation of menstruation and restoration of ovulation occur later and almost coincide with each other." (PMID 33426414, 2020).